AQP4 (aquaporin 4)
Diseases named in the same sentence as AQP4 in open-access papers (continued):
Sharing a sentence is not in itself a finding about the gene and the disease.
neuromyelitis optica spectrum disorder (continued). "Neuromyelitis optica spectrum disorders (NMOSDs) are attack-relapsing autoimmune inflammatory diseases of the central nervous system, which are characterized by the presence of serological aquaporin-4 (AQP4) antibody." (PMID 35250969, 2022). "Antibodies directed against AQP-4 are characteristically found in patients suffering from neuromyelitis optica (NMO), a demyelinating disease of the CNS that mainly affects the optic nerve and the spinal cord." (PMID 36241864, 2022). "Neuromyelitis optica spectrum disorder (NMOSD) is a relapsing autoimmune disease characterized by the presence of pathogenic autoantibodies, anti-aquaporin 4 (AQP4) antibodies." (PMID 34997058, 2022). "A study of T-cell proliferation to peptides of aquaporin-4 in neuromyelitis optica patients also used SI > 2 as their cutoff value." (PMID 35173742, 2022). "Eculizumab is an anti-C5 monoclonal antibody considered as a treatment option for neuromyelitis optica, preventing the aquaporin-4 mediated complement-induced damage." (PMID 35976311, 2022). "Weiterhin gibt es Fallberichte über das Auftreten AQP4-seropositiver Neuromyelitis-optica-Spektrum-Erkrankungen (NMOSD) nach COVID-19, in einem Fall mit einer vergleichsweise langen Latenz von 3 Monaten nach der Akutinfektion." (PMID 35552466, 2022). "Serum antibodies to myelin-oligodendrocyte glycoprotein (MOG) are biomarkers of MOG-IgG-associated disorder (MOGAD), a demyelinating disease distinct from both multiple sclerosis and aquaporin-4-IgG neuromyelitis optica spectrum disorder." (PMID 36002821, 2022). "Neuromyelitis optica spectrum disorder (NMOSD) is an autoimmune astrocytopathy against foot processes of aquaporin-4 (AQP4) water channels." (PMID 35864917, 2022). "cerevisiae antibody (ASCA) were more frequent in patients affected by AQP4-seropositive neuromyelitis optica compared to controls." (PMID 35979352, 2022). "Neuromyelitis optica spectrum disorder (NMOSD) is an autoimmune disorder affecting the central nervous system and associated with the presence of aquaporin-4 immunoglobulin G antibodies (AQP4-IgG)." (PMID 35761294, 2022). "AQP4 plays a key role in CNS entities such as encephaledema, brain tumor, epilepsy, and neuromyelitis optica." (PMID 35991296, 2022). "The patient was tested positive for serum anti-aquaporin-4 antibody (AQP4-Ab) and was diagnosed with neuromyelitis optica spectrum disorder (NMOSD)." (PMID 35402220, 2022). "AQP4 is known to be altered in several neurological conditions, including tumours, neuromyelitis optica, autism spectrum disorders, AD, ALS, multiple sclerosis (MS), stroke, epilepsy and as a consequence of traumatic brain injury." (PMID 36499600, 2022). "Neuromyelitis optica is characterized by the presence of IgG1 autoantibodies that attack aquaporin 4 (AQP4), a predominant water channel in the CNS." (PMID 36341463, 2022). "J Neuromyelitis optica spectrum disorder following COVID-19 infection with increase in pre-existing anti-aquaporin-4 antibodies." (PMID 35552466, 2022). "Serum Neuromyelitis Optica antibody (AQP4-IgG) and Myelin oligodendrocyte glycoprotein antibody (MOG-IgG) were negative." (PMID 35305566, 2022). "Neuromyelitis optica spectrum disorder (NMOSD) is an autoimmune‐related neurological disease characterized by the presence of serum anti‐aquaporin‐4 autoantibodies (AQP4‐IgG)." (PMID 33591639, 2021). "A paraneoplastic etiology has been reported in few patients with aquaporin-4 (AQP4)-IgG-seropositive neuromyelitis optica spectrum disorders (NMOSD), with lung and breast cancer being the most frequent associated malignancies." (PMID 33078290, 2021). "Eculizumab is currently approved for treatment of aHUS and recently for neuromyelitis optica spectrum disorder (NMOSD) with aquaporin‐4 antibodies (AQP4‐IgG)." (PMID 33325640, 2021). "As an intracellular protein, GFAP cannot be up- or down-regulated on the cell surface, and a similar situation also applies to AQP4 in neuromyelitis optica." (PMID 34880859, 2021).
neuromyelitis optica spectrum disorder (continued). "In line with this, a recent study on neuromyelitis optica, an autoimmune disease where anti-AQP4 antibodies are formed, correlated Müller cell dysfunction with electrophysiological disturbances in affected patients." (PMID 33503976, 2021). "Material and Methods: We included three groups—a group of patients with AQP4–IgG-positive neuromyelitis optica, a healthy group, and a sham group." (PMID 34068922, 2021). "Inebilizumab, a humanized mAb targeting CD19, received FDA approval for the treatment of neuromyelitis optica spectrum disorder (NMOSD) in adult patients who are seropositive for immunoglobulin G autoantibodies against aquaporin-4 (AQP4-IgG) in June 2020." (PMID 33530460, 2021). "This pandemic has also raised health concerns for patients with neuromyelitis optica spectrum disorder (NMOSD), a chronic, relapsing autoimmune disorder of the central nervous system mainly associated with antibodies against aquaporin-4 (AQP4) water channels." (PMID 33828524, 2021). "Neuromyelitis optica spectrum disorder (NMOSD) is a severe inflammatory disorder of the central nervous system (CNS) with an autoantibody against aquaporin-4 protein (AQP4)." (PMID 33879715, 2021). "Neuromyelitis optica spectrum disorder (NMOSD) is a severe inflammatory disorder of the central nervous system with an autoantibody against aquaporin-4 protein (AQP4), and amyotrophic lateral sclerosis (ALS) is a fatal neurodegenerative disease." (PMID 33879715, 2021). "This study was performed in order to investigate the patterns of neurochemical changes in lesioned tissue and in normal appearing white matter in multiple sclerosis (MS) and aquaporin-4 antibody positive neuromyelitis optica spectrum disorder (AQP4Ab-NMOSD)." (PMID 34062267, 2021). "Some years ago, autoantibodies against astrocyte antigen AQP4 has been discovered in a subset of patients with neuromyelitis optica spectrum disorders (NMOSD)." (PMID 34149706, 2021). "The aim of this study was to report the possible association between minor trauma to the eyes and the subsequent occurrence of optic neuritis in patients with serum anti‐aquaporin‐4 (AQP4) antibody‐positive neuromyelitis optica spectrum disorder (NMOSD)." (PMID 33591639, 2021). "Patients with neuromyelitis optica also suffer from severe pain due to dysregulation of astrocytes and generation of aquaporin-4 autoantibodies." (PMID 34804074, 2021). "Neuromyelitis optica spectrum disorder (NMOSD) is mainly an anti-aquaporin 4 (anti-AQP4) autoantibodies-mediated idiopathic inflammatory demyelinating disease of the central nervous system." (PMID 34526069, 2021). "Summary of the results of family studies in neuromyelitis optica [HLA, human leukocyte antigen, AQP4-Ab, aquaporin-4 antibody (NMO-IgG)]." (PMID 34675927, 2021). "Neuromyelitis optica spectrum disorder (NMOSD) is an antibody-mediated autoimmune disease of the CNS in which the primary target for inflammation is aquaporin 4 (AQP4), a water channel found on the foot processes of astrocytes." (PMID 34566866, 2021). "Circulating T helper cells with a type 17-polarized phenotype (TH17) and expansion of aquaporin-4 (AQP4)-specific T cells are frequently observed in patients with neuromyelitis optica spectrum disorder (NMOSD)." (PMID 34335563, 2021). "Three novel autoantibodies other than AQP4 were detected in the serum of one patient with Devic’s neuromyelitis optica." (PMID 34012435, 2021). "For example, the conventional serological marker to separate neuromyelitis optica (NMO) from MS is the presence of aquaporin-4 (AQP4) antibodies in NMO patients." (PMID 33449145, 2021). "The discovery of disease-specific antibodies against AQP4 in the sera from patients with neuromyelitis optica resulted in significant progress regarding this concern." (PMID 33917929, 2021).
neuromyelitis optica spectrum disorder (continued). "Neuromyelitis optica spectrum disorder (NMOSD) is an inflammatory demyelinating disease mediated by inflammation against the aquaporin-4 (AQP4) water channel on astrocytes predominantly attacked optic nerves and spinal cord." (PMID 34987355, 2021). "The changes in the serum levels of aquaporin-4-IgG (AQP4-IgG), immunoglobulins, and inflammatory mediators in neuromyelitis optica spectrum disorder (NMOSD) cases treated with immunoadsorption have been rarely described in detail." (PMID 34367127, 2021). "Another study showed that 27% of patients with AQP4‐positive neuromyelitis optica were diagnosed with cancer shortly before and after diagnosis." (PMID 34520629, 2021). "The role of NLR in AQP4-IgG-positive neuromyelitis optica spectrum disorders (NMOSD) is far from clear." (PMID 33717149, 2021). "For example, autoantibodies targeting the aquaporin-4 (AQP4) channel, which is enriched on the surface of astroglial cells and involved in maintaining integrity of the blood brain barrier, cause neuromyelitis optica (NMO/Devic’s disease)." (PMID 33763057, 2021). "Neuromyelitis optica spectrum disorders (NMOSD) is recognized as a distinct clinical entity from multiple sclerosis (MS) based on the disease-specific serum autoantibody aquaporin-4 (AQP4)-IgG." (PMID 32983166, 2020). "A diagnosis of neuromyelitis optica spectrum disorder with positive aquaporin-4 antibodies has finally been established." (PMID 33102404, 2020). "Pathogenic autoantibodies directed against the water channel aquaporin 4 (AQP4) are found in the vast majority of patients with neuromyelitis optica spectrum disorders (NMOSD)." (PMID 32293546, 2020). "Neuromyelitis optica spectrum disorder (NMOSD), an autoimmune astrocytopathic disease associated with the anti-aquaporin-4 (AQP4) antibody, is characterized by extensive necrotic lesions primarily located on the optic nerves and spinal cord." (PMID 32586353, 2020). "Several studies showed that passive transfer alone of the aquaporin-4 antibody from patients with neuromyelitis optica is insufficient to reproduce the disease in rodents unless extremely high levels are infused." (PMID 33224094, 2020). "This process is especially relevant to certain pathologies, including neuromyelitis optica, where antibodies target AQP4 and can result in the internalization of plasmalemmal isoforms of AQP4, which are then passed on to early endosomes." (PMID 32192013, 2020). "Neuromyelitis optica spectrum disorder (NMOSD) is an inflammatory disease of the CNS characterized by auto-antibodies against the water-channel aquaporin-4 (AQP4)." (PMID 33391273, 2020). "Neuromyelitis optica spectrum disorders (NMOSD) is a primary astrocytopathy driven by antibodies directed against the aquaporin-4 water channel located at the end-feet of the astrocyte." (PMID 32881954, 2020). "Autoantibodies against aquaporin-4 (AQP4-Ab) and myelin oligodendrocyte glycoprotein (MOG-Ab) are associated with rare central nervous system inflammatory demyelinating diseases like neuromyelitis optica spectrum disorders (NMOSD)." (PMID 32625206, 2020). "Following a phase III trial, eculizumab was approved by the FDA in 2019 to treat neuromyelitis optica in patients who test positive for anti-aquaporin-4 antibodies." (PMID 33013859, 2020). "Studies have also highlighted possible links between AQP4 and infectious and neuroinflammatory diseases, most notably meningitis, malaria and neuromyelitis optica (NMO)." (PMID 33167342, 2020). "Longitudinally extensive transverse myelitis (LETM) is classically related to aquaporin (AQP4)-antibodies (Ab) neuromyelitis optica spectrum disorders (NMOSD) or more recently to myelin oligodendrocyte glycoprotein (MOG)-Ab associated disease." (PMID 32326965, 2020). "One example, therefore, is the very high levels of GFAP in the serum of neuromyelitis optica patients, where especially aquaporin-4 positive astrocytes are damaged." (PMID 32765393, 2020).
neuromyelitis optica spectrum disorder (continued). "Following the discovery that AQP4 is a possible autoantigen in neuromyelitis optica, the function of AQP4 in health and disease has become a research focus." (PMID 32998402, 2020). "We concluded that AQP4-IgG-positive neuromyelitis optica spectrum disorder (NMOSD) was concurrent with VZV myelitis." (PMID 33329330, 2020). "Neuromyelitis optica spectrum disorder (NMOSD) is a rare and severe auto-immune disease of the central nervous system driven by pathogenic antibodies mainly directed against aquaporin-4 (AQP4-Ab)." (PMID 31803192, 2019). "Neuromyelitis optica spectrum disorder (NMOSD) is an inflammatory disease of the central nervous system characterized by severe relapses in regions with high aquaporin 4 (AQP4) expression such as the optic nerves, the spinal cord and specific brain areas." (PMID 30695058, 2019). "At age 24, she was found to have elevated titers of aquaporin-4 antibodies in serum, suggestive of probable neuromyelitis optica." (PMID 30696485, 2019). "Further studies of aquaporin-4 microparticles in cerebrospinal fluid of patients with neuromyelitis optica and similar neuropsychiatric disorders are thus called for." (PMID 30696485, 2019). "We measured extracellular aquaporin-4 microparticles in the cerebrospinal fluid of a patient who later developed the typical symptoms and signs of a neuromyelitis optica spectrum disorder." (PMID 30696485, 2019). "This study provides the first direct evidence in vivo on the specific role of AQP4ex in AQP4 perivascular OAPs assembly and confinement and reveals AQP4ex as new and important player in neuromyelitis optica." (PMID 30935410, 2019). "Astrocytes enhanced survival of co-cultured neurons and were killed by Aquaporin-4 antibody positive sera from patients with Neuromyelitis optica." (PMID 31474831, 2019). "We found a significant increase of extracellular microparticles of aquaporin-4 in cerebrospinal fluid sampled from our patient when she was 22 years old, 2 years before the full clinical development of neuromyelitis optica." (PMID 30696485, 2019). "The increase of aquaporin-4 microparticles in cerebrospinal fluid may be used for early diagnostic purposes; for prevention; and for evaluation of effective treatment, long-term follow-up studies, and elucidating the pathophysiology in neuromyelitis optica spectrum disorders." (PMID 30696485, 2019). "Within the CNS autoimmunity control cohort, autoantibodies against aquaporin 4 and high-titer Abs against myelin oligodendrocyte glycoprotein were, as expected, specific for neuromyelitis optica spectrum disorders." (PMID 30824481, 2019). "Aquaporin 4 antibodies (AQP4-ab) were positive and she was diagnosed with neuromyelitis optica (NMO)." (PMID 31163654, 2019). "The detection of IgG aquaporin-4 antibodies in the serum of patients with Neuromyelitis optica (NMO) has dramatically improved the diagnosis of this disease and its distinction from multiple sclerosis." (PMID 31752329, 2019). "The presence of serum AQP4-Abs identifies acquired demyelinating syndromes of the CNS mainly affecting the optic nerves and spinal cord, collectively defined as Neuromyelitis Optica Spectrum Disorders (NMOSD), which are in differential diagnosis with MS." (PMID 32010046, 2019). "In comparison to children with AQP4-positive neuromyelitis optica spectrum disorder (NMOSD), those with MOG-AD tend to be younger, less likely to present with area postrema syndrome, but more likely to present with ADEM." (PMID 30569382, 2019). "The first one is neuromyelitis optica in which an antibody response against aquaporin-4 targets and destroys astrocytes, the second, likely distinct entity embraces a group of patients containing antibodies against myelin oligodendrocyte glycoprotein." (PMID 30800132, 2019). "The discovery of NMO-IgG and AQP4 as its targeted antigen unequivocally confirmed neuromyelitis optica as a disease distinct from MS and allowed its early laboratorial recognition." (PMID 31212763, 2019).
neuromyelitis optica spectrum disorder (continued). "MOG-Abs are consistently identified in a range of acquired demyelinating syndromes (ADS) in adults and children with a clinical phenotype distinct of MS and AQP4-Ab neuromyelitis optica spectrum disorder." (PMID 30671648, 2019). "We have compared five different assays for antibodies to aquaporin-4 in 181 cases of suspected Neuromyelitis optica spectrum disorders (NMOSD) and 253 controls to assess their relative utility." (PMID 31636597, 2019). "Aquaporin-4 (AQP4) and S100B have been linked to increased permeability of the blood-brain barrier (BBB), neuromyelitis optica, and dementia, among others." (PMID 30034864, 2018). "Antibodies against plant AQP4 from tomato, corn, soy, spinach, and human AQP4 have been detected in patients with MS and neuromyelitis optica." (PMID 30034864, 2018). "Neurofilaments in the differential diagnosis of ALS or the presence of anti-aquaporin 4 antibodies in neuromyelitis optica are quite sensitive and specific, but only when applied in the correct diagnostic context." (PMID 29544527, 2018). "Neuromyelitis optica spectrum disorder-optic neuritis (NMOSD-ON) can now be distinguished from other types of ON as a specific disease by the Aquaporin-4 antibody (AQP4-Ab) test." (PMID 30217177, 2018). "Neuromyelitis optica immunoglobulin G was discovered in 2004 as a serum autoantibody biomarker of neuromyelitis optica, and subsequently confirmed to be IgG autoantibodies targeting aquaporin-4 (AQP4–IgG)." (PMID 29988553, 2018). "We used the search terms “neuromyelitis optica,” “neuromyelitis optica spectrum disorder,” “MOG,” aquaporin-4 antibodies,” “MRI,” “diagnostic criteria,” “therapy,” and combinations of these." (PMID 30405519, 2018). "The field of central nervous system (CNS) inflammatory demyelinating diseases (IDD) has undergone considerable change with the discovery of antibodies against the aquaporin-4 water channel (AQP4-Ab) in neuromyelitis optica spectrum disorders (NMOSD)." (PMID 29208041, 2017). "Neuromyelitis optica patients have lesions in areas of high AQP4 expression, such as the brain, optic nerve, and spinal cord." (PMID 28955334, 2017). "Although rare, brain abnormalities without optic neuritis (ON) or transverse myelitis (TM) diagnosed with neuromyelitis optica spectrum disorder (NMOSD) have been reported in patients positive for the aquaporin-4 (AQP4) antibody." (PMID 28293214, 2017). "Anti-AQP4 autoantibodies are detected in patients with neuromyelitis optica, and the presence of anti-AQP4 IgG in the sera is used as a gold standard for the differential diagnosis of neuromyelitis optica from multiple sclerosis." (PMID 26786004, 2016). "Aquaporin 4 (AQP4) is considered a putative autoantigen in patients with Neuromyelitis optica (NMO), an autoinflammatory disorder of the central nervous system (CNS)." (PMID 27054574, 2016). "We characterized a unique group of patients with neuromyelitis optica spectrum disorder (NMOSD) who carried autoantibodies of aquaporin-4 (AQP4) and myelin-oligodendrocyte glycoprotein (MOG)." (PMID 26920678, 2016). "The discovery of a highly specific antibody against the aquaporin-4 (AQP4) water channel (AQP4-IgG) unified the spectrum of neuromyelitis optica spectrum disorders (NMOSD), which are considered to be antibody-mediated autoimmune diseases." (PMID 27371173, 2016). "Antibodies against MOG (MOG-IgG) have been detected in a proportion of aquaporin-4 (AQP4)-IgG-seronegative patients with neuromyelitis optica spectrum disorder (NMOSD) phenotype." (PMID 27802824, 2016). "We aimed to investigate the frequency of asymptomatic acute brain MRI abnormalities accompanying optic neuritis (ON) or myelitis in neuromyelitis optica spectrum disorder (NMOSD) patients with aquaporin-4 antibodies (AQP4-Ab)." (PMID 27936193, 2016). "Currently, the standard method to detect anti-AQP4 autoantibodies for the diagnosis of neuromyelitis optica is with IIFA." (PMID 26786004, 2016).